AKT1 (AKT serine/threonine kinase 1)
Diseases named in the same sentence as AKT1 in open-access papers (continued):
Sharing a sentence is not in itself a finding about the gene and the disease.
schizophrenia (continued). "WDFY2 is not directly associated with BD, but its product interacts with AKT1, which has been found involved in BD and schizophrenia." (PMID 29257106, 2017). "AKT1 is also especially relevant to intrinsic metabolic risk in schizophrenia since it is an important regulator of insulin signaling." (PMID 28804444, 2017). "The AKT1 isoform specifically has been linked to schizophrenia, a neurological disorder believed to represent brain dysconnectivity with a molecular basis in aberrant synaptic plasticity." (PMID 29173281, 2017). "Study of the effects of schizophrenia-risk associated AKT3 polymorphisms (as previously done for AKT1) on neuroanatomical structure and neurocognitive function in normal human subjects, is warranted." (PMID 28467426, 2017). "The findings of this study contribute to a recent and growing body of evidence suggesting that variation at the AKT1 locus confers details of the risk of cannabis smoking for schizophrenia." (PMID 26882038, 2016). "The associations between schizophrenia and AKT1 genetic variants have been well established, and decreased levels of Akt1 and substrate phosphorylation have been reported in the brain of individuals suffering from the disorder." (PMID 26877878, 2016). "The mechanisms underlying the sex-specific effect of Akt1 and the effects of hormones (e.g., oestrogen) on GABAergic transmission and the pathogenesis of schizophrenia merit further investigation in future studies." (PMID 27615800, 2016). "The biological functions of Akt1 and the mechanism by which Akt1 contributes to susceptibility for schizophrenia are currently under intensive investigation." (PMID 27615800, 2016). "A meta-analysis of AKT1 has demonstrated that rs2494732 (A>G) located at 3′-UTR of the AKT1 gene was significantly associated with schizophrenia." (PMID 26694375, 2015). "For example, four single-nucleotide polymorphisms (SNPs) (rs2237717, rs41735, rs42336, and rs1858830) of the MET gene and the rs1130233 SNP of the AKT1 gene have been associated with schizophrenia and with neurocognitive performance." (PMID 24955105, 2014). "Akt itself has been implicated as a risk factor for schizophrenia susceptibility, as a specific AKT1 haplotype causes decreased Akt levels and is associated with illness." (PMID 24672476, 2014). "Reductions in AKT1 expression and function have been implicated in schizophrenia in a number of recent studies." (PMID 25505409, 2014). "Evidence for AKT1 as a susceptibility gene for schizophrenia was reported in Caucasian families of European descent originally and subsequently in several other populations." (PMID 25688191, 2014). "The biological functions of AKT1 and the mechanism by which it contributes to a susceptibility to schizophrenia need further investigation." (PMID 25688191, 2014). "Other genetic studies demonstrated association of AKT1 gene polymorphisms with schizophrenia in Chinese, Irish, British, Japanese, Iranian, and European populations." (PMID 24403877, 2013). "Significant reduction of AKT1 expression and deregulation of AKT1-associated pathways have recently also been reported in peripheral blood cells of schizophrenia patients." (PMID 23369358, 2013). "The study further found that schizophrenia patients carrying risk alleles of Akt1 and DRD2 genes which influence D2 receptor function had less illness-related reductions in IQ levels with higher doses of antipsychotics than non-risk allele carriers." (PMID 23449679, 2012). "Our findings significantly extend the work done in association studies on AKT1 and schizophrenia by showing decreased gene expression in a naturalistically obtained patient sample." (PMID 22393424, 2012). "Since the initial report of deregulated AKT1 in schizophrenia, several case/control samples and family cohorts showed an association between schizophrenia and AKT1 genetic variants." (PMID 22393424, 2012).
schizophrenia (continued). "For example, PI3K/AKT/mTOR signaling is altered in models of schizophrenia, and several single nucleotide polymorphisms (SNPs) in the AKT1 gene have been associated with the development of the disease as well as with total AKT1 protein levels." (PMID 21949775, 2011). "AKT1 signaling mediates a number of critical neuronal signaling molecular pathways that are implicated in schizophrenia and also plays a central role in tumorigenesis in many cancers." (PMID 20520724, 2010). "Our study suggested a possible role for the AKT1 gene in obstetric complications; the association was more notable in female patients with schizophrenia." (PMID 20046382, 2009). "We found an association between SNPs in the AKT1 gene and total Lewis score measuring obstetric complications in female patients with schizophrenia." (PMID 20046382, 2009). "These patients have been genotyped for six SNPs of AKT1 to identify a possible association with a schizophrenia diagnosis." (PMID 20046382, 2009). "We found an association in female patients with schizophrenia between the SNPs in the AKT1 gene and total Lewis score measuring obstetric complications." (PMID 20046382, 2009). "We previously have shown that polymorphisms in the PPP1R1B and in AKT1 linked to increased striatal frontal connectivity and decreased striatal volume were associated with genetic risk for schizophrenia." (PMID 18989458, 2008). "When AKT1 is mutated, it can increase the risk of schizophrenia." (PMID 37999247, 2023). "Some findings may link GSK-3 with the disease: first, GSK-3 is associated with schizophrenia susceptibility genes such as Akt1, DISC1, and TRAX (Translin-associated protein X)." (PMID 35126052, 2021). "Double deficiency of Akt1 and Nrg1 can result in the impairment of social cognitive functions, which might be pertinent to the pathogenesis of schizophrenia-related social cognition which related to schizophrenia." (PMID 29156812, 2017). "Nevertheless, two genes associated with schizophrenia, AKT1 and neuregulin 1 (NRG1), may also play roles in systemic metabolic regulation." (PMID 28804444, 2017). "In particular, Akt1 was originally identified as a potential schizophrenia susceptibility gene." (PMID 28442992, 2017). "AKT1 is considered to be a potentially susceptible gene for the development of schizophrenia." (PMID 26877878, 2016). "Accumulating evidence from human genetic studies has suggested several functional candidate genes that might contribute to susceptibility to schizophrenia, including AKT1 and neuregulin 1 (NRG1)." (PMID 25688191, 2014). "Collectively, our results indicate that double deficiency of Akt1 and Nrg1 can result in the impairment of social cognitive functions, which might be pertinent to the pathogenesis of schizophrenia-related social cognition." (PMID 25688191, 2014). "AKT1-deficient mice show alterations in the dendritic architecture of mPFC pyramidal neurons as well as working memory deficits that are believed to be representative of analogous deficits found in schizophrenia." (PMID 25505409, 2014). "Recent studies have suggested that deregulated AKT1 signaling is associated with schizophrenia." (PMID 22393424, 2012). "Our findings implicate genetic and functional interactions between COMT and AKT1 and may provide novel insights into pathogenesis of schizophrenia and other ErbB-associated human diseases such as cancer." (PMID 20520724, 2010). "Since COMT, AKT1, and ErbB-signaling are each implicated in both cancer and schizophrenia, NRG1-ErbB signaling in B lymphoblasts provides a biologically plausible research tool for elucidating cellular mechanisms relevant to both cancer biology and neurobiology." (PMID 20520724, 2010). "Interestingly, both COMT and AKT1 have also been implicated in the pathogenesis of cancer and schizophrenia, and their associations with these disease conditions have been extensively studied." (PMID 20520724, 2010).
schizophrenia (continued). "A dysregulation in AKT1 function, possibly due to genetic mutation, could cause schizophrenia developmentally through a hypoxic insult to the fetal brain or through other genetic effects on the brain function of schizophrenic patients." (PMID 20046382, 2009). "Also, an AKT1 haplotype linked to lower AKT1 protein levels was associated with schizophrenia." (PMID 35111368, 2022). "Because protein synthesis is crucial to maintain L-LTP, our finding that Akt1 deletion results in the impairment of L-LTP and the associated protein synthesis response suggests AKT1 may be an important factor in the synaptic and cognitive deficits observed in schizophrenia." (PMID 29173281, 2017). "For example, a decrease in AKT1 protein levels and levels of phosphorylation of GSK3β at Ser9 in the peripheral lymphocytes and brains of individuals with schizophrenia was reported." (PMID 41510670, 2026). "A study found that the expression levels of AKT1 significantly increased in acute schizophrenia patients, which is consistent with our result." (PMID 40078531, 2025). "We found a significant increase in the expression of protein kinases AKT1 and p706SK in mononuclear cells of patients with schizophrenia compared to healthy individuals (p = 0.006 and p = 0.001)." (PMID 41283305, 2025). "In contrast, decreased AKT1 expression was observed in the dorsolateral prefrontal cortex of individuals with schizophrenia and bipolar disorder, with a significant reduction in schizophrenic patients and a moderate effect size in bipolar patients." (PMID 39518903, 2024). "It has been found that the abnormal expression of AKT1 is related to schizophrenia, bipolar disorder, Parkinson’s disease and other diseases." (PMID 38533261, 2024). "Polymorphisms in AKT1 (rs1130233 and rs2494732) were associated with low brain AKT protein expression and the development of schizophrenia." (PMID 37185752, 2023). "AKT serine/threonine kinase 1 (AKT1) acts downstream of the dopamine D2 receptor and has also been associated with schizophrenia in several studies." (PMID 36980961, 2023). "Our findings demonstrate that HERV-W ENV triggered the hyperactive dopaminergic system via the DRD2/PP2A/AKT1/GSK3 cascade in schizophrenia." (PMID 35062349, 2022). "AKT1 down-stream targets, such as GSK3β, are also altered in schizophrenia, including a decreased level of GSK-3β protein phosphorylation and GSK-3β mRNA in the prefrontal cortex." (PMID 35625659, 2022). "This new mechanism is in agreement with observations showing altered Wnt pathway genes such as GSK3β, WIF1, as well as AKT1 in schizophrenia postmortem brains." (PMID 36131044, 2022). "It has been repeatedly reported that there is decreased expression of AKT1 mRNA and protein levels in the prefrontal cortex and hippocampus in patients with schizophrenia." (PMID 35625659, 2022). "Research into peripheral lymphocyte signaling in antipsychotic-naive schizophrenia patients found not only reduced Akt1 levels but also that the level of Stat3 phosphorylation in immune cells predicted improvements in general psychopathology scores." (PMID 35844244, 2022). "Protein levels of AKT3 family member AKT1 are significantly reduced in lymphocytes and the brain of individuals diagnosed with schizophrenia." (PMID 36386965, 2022). "For example, a decrease in AKT1 levels and GSK3β phosphorylation were found in the peripheral lymphocytes and brains of schizophrenia patients." (PMID 35111368, 2022). "It was shown that the expression and activity of AKT1 were reduced in lymphocytes and in the frontal cortex and hippocampus of individuals with schizophrenia." (PMID 33552387, 2021). "Along with previous findings, our current results in Akt1+/− female mice suggest the importance of AKT1-GSK3 signaling in schizophrenia and treatment selection." (PMID 31959776, 2020).
schizophrenia (continued). "Collectively, our findings supported the therapeutic potential of lithium for the treatment of schizophrenia and the importance of Akt1-Gsk3 as a therapeutic target." (PMID 31959776, 2020). "AKT1 protein levels were diminished both in peripheral lymphocytes and in the brains of people with schizophrenia." (PMID 28804444, 2017). "A potential explanation of this apparent discrepancy is that AKT1 protein levels are diminished in people with schizophrenia." (PMID 28804444, 2017). "The levels of AKT1 are reduced in the prefrontal cortex and the hippocampus of postmortem brains, as well as in the peripheral lymphocytes of individuals with schizophrenia." (PMID 26877878, 2016). "Our model also offers an explanation for the consistent downregulation of AKT1 in recent-onset schizophrenia." (PMID 26450699, 2015). "Further, the gene product has been implicated in schizophrenia: postmortem studies have shown decreased AKT1 levels in lymphoblasts in the PFC of patients with schizophrenia." (PMID 24904437, 2014). "These include NOS1, AKT1, DTNBP1, DNMT1, PPP3CC and SOX10, which have previously been associated with schizophrenia." (PMID 24399042, 2014). "Our observations suggest that decreased PBMC AKT1 expression is a stable trait in recent onset, male schizophrenia patients." (PMID 22393424, 2012). "Taken together, our observations suggest that decreased PBMC AKT1 expression is a stable trait in recent onset, male schizophrenia patients." (PMID 22393424, 2012). "We show significantly decreased PBMC gene expression of AKT1 in male, recent-onset schizophrenia patients." (PMID 22393424, 2012). "In conclusion, we show decreased PBMC gene expression of AKT1 in schizophrenia patients, with a considerable effect size, which allowed detection in two relative small cohorts." (PMID 22393424, 2012). "Emamian and colleagues demonstrated reduced AKT1 protein expression in B lymphoblasts and postmortem brain tissues from patients with schizophrenia." (PMID 20520724, 2010). "The present findings offer an additional facet to COMT's biology that has new, broad and potentially important implications for cancer biology and schizophrenia via its interaction with AKT1." (PMID 20520724, 2010). "For example, studies show diminished Akt1 protein content in lymphocytes of patients with schizophrenia." (PMID 20543991, 2010). "In terms of neural apoptosis, HERV-W env triggers aberrant dopaminergic neuronal processes via DRD2/PP2A/AKT1/GSK3 for schizophrenia risk and promotes antiviral immune response in schizophrenia through the linc01930/cGAS/STING pathway, resulting in neuronal apoptosis." (PMID 40128823, 2025). "Our earlier research revealed for the first time a novel connection between specific gene polymorphisms related to neuroplasticity and protein kinases (including MAPK, BDNF, GSK3β, and AKT1) and the development of schizophrenia symptoms that predict a poor disease outcome." (PMID 41283305, 2025). "Thus, our study demonstrates significant changes in the expression level of intracellular AKT1 and p706SK kinases in patients with schizophrenia." (PMID 41283305, 2025). "This study found that prenatal Poly I:C challenge led to an increased mRNA expression of AKT1, AKT3, and GSK3β in the DRN; therefore, our findings provided the first evidence in the DRN to support the proposition that alterations in AKT‐GSK3β signaling contribute to schizophrenia pathogenesis." (PMID 40562368, 2025). "Furthermore, AKT1 (protein kinase B) and GABAA receptor genes are associated with disrupted cognitive functions in a mice model of schizophrenia." (PMID 39399446, 2024). "This study demonstrates elevated mRNA expression of AKT1-3 in neurons from schizophrenia subjects, contrary to unchanged or diminished total AKT protein expression reported in previous postmortem studies, suggesting a potential decoupling of transcript and protein levels." (PMID 38559131, 2024).
schizophrenia (continued). "The level of protein AKT1 was 68% lower in patients with schizophrenia than in the controls." (PMID 37185752, 2023). "Recent studies show that it may be important in regulating the development of neuronal progenitor cells, and physically interacts with other schizophrenia susceptibility genes, such as CREB1, AKT1 and ESR1." (PMID 35576194, 2022). "Reduced AKT1 protein levels are also reported in schizophrenia patients." (PMID 35062349, 2022). "Furthermore, the bagging ensemble algorithm with feature selection surpassed other predictive algorithms to forecast the GAF functional outcome of schizophrenia by using the AKT1 rs1130233 SNP." (PMID 33986383, 2021). "The interaction of four single nucleotide polymorphism (SNP) loci, rs1130214 (AKT1), rs456998 (FCHSD1), rs7211818 (RAPTOR), and rs1053639 (DDIT4), was reported to predict the extrapyramidal response of patients with schizophrenia after using antipsychotic drugs." (PMID 34348681, 2021). "Consequently, the activity of the major AKT1 target—GSK-3—is altered in patients with schizophrenia." (PMID 31191636, 2019). "AKT1 is one of the effectors in the well-established pathway from neuregulin 1 (NRG1-ERBB4-PI3K-AKT1 pathway), where each of these components have genetic polymorphisms that have been linked to schizophrenia." (PMID 29173281, 2017). "These polymorphisms may lead to lower AKT1 protein levels in schizophrenia, although increased AKT1 expression and activity also have been reported in schizophrenia." (PMID 29173281, 2017). "It is important to note that it is currently unknown whether the decrease in AKT Ser473 phosphorylation observed in patients with schizophrenia is accounted for by alterations in the activity of AKT1, AKT2 or AKT3." (PMID 28467426, 2017). "Furthermore, evidence from postmortem brain and peripheral cells of patients with schizophrenia has identified reduced AKT activity, either through reduced expression of AKT1, AKT3 or phosphorylated AKT Ser473." (PMID 28467426, 2017). "Together, these reports may suggest protein synthesis is reduced in schizophrenia, which may be due to reduced AKT1 signaling." (PMID 29173281, 2017). "Our findings also support the involvement of Akt1 in the modulation of parvalbumin-positive interneurons and GABAergic signalling, thereby implicating Akt1 in the GABA hypothesis of schizophrenia." (PMID 27615800, 2016). "It is of great interest to investigate how Akt1 regulates GABA signalling and GABA-related cognitive functions that might contribute to the pathogenesis of schizophrenia and its associated cognitive deficits." (PMID 27615800, 2016). "AKT1 has been found to be downregulated in schizophrenia and its downregulation is thought to be instrumental in abnormal hippocampal neuroplasticity and cognition in schizophrenia." (PMID 26450699, 2015). "A number of studies have reported a genetic association between AKT1 and schizophrenia; other studies failed to support these results." (PMID 26694375, 2015). "Moreover, it has been shown that the expressed protein levels of AKT1 significantly decreased in the postmortem frontal cortex and hippocampus of patients with schizophrenia compared to controls." (PMID 26694375, 2015). "The roles of AKT1 and NRG1, either alone or their interaction, through which they might contribute to a susceptibility to social function in schizophrenia are worth further investigation." (PMID 25688191, 2014). "Genetic linkage analyses showed co-segregation of Akt1 haplotypes with schizophrenia, suggesting that the AKT1 gene may be a schizophrenia susceptibility gene." (PMID 24403877, 2013). "For example, expression of other actin-related or cytoskeletal proteins has been implicated in schizophrenia and bipolar disorder, and several schizophrenia susceptibility genes interact with actin and the cytoskeleton, including DISC1, calcineurin, Akt1 and dysbindin." (PMID 22675524, 2012).